CRP (C-reactive protein)
Diseases named in the same sentence as CRP in open-access papers (continued):
Sharing a sentence is not in itself a finding about the gene and the disease.
end-stage renal disease (61 papers, 2010 to 2026). "The level of CRP in CKD patients is significantly elevated, and the baseline level of CRP is closely related to the risk of developing end-stage renal disease or death in patients." (PMID 39371339, 2024). "The combination of CRP and troponin has been sporadically evaluated jointly to evaluate the risk of cardiac disease and death in stable end-stage renal failure patients on dialysis or to assess prognosis in acute coronary patients." (PMID 33886564, 2021). "High P-NEAC levels (FRAP) were also inversely associated with CRP levels among 80 patients with End-Stage Renal Failure." (PMID 32260517, 2020). "Clinically, higher baseline levels of IL-6 and C-reactive protein predict faster eGFR decline and progression to end-stage renal disease in human CKD cohorts, and elevated circulating TNF receptors 1 and 2 have been shown to forecast ESRD in diabetic patients." (PMID 40990676, 2026). "Soluble interleukin-2 receptor was high, but end-stage renal failure and high CRP value made it difficult for us to consider it a meaningful elevation." (PMID 41001313, 2025).
lymphoma (61 papers, 1983 to 2026). A malignant (clonal) proliferation of B- lymphocytes or T- lymphocytes which involves the lymph nodes, bone marrow and/or extranodal sites. "Elevated CRP has been linked with advanced disease stage and poor prognosis in both human and canine cancers, including lymphoma and solid tumors." (PMID 40552079, 2025). "CRP has been identified as a prognostic factor in various hematological malignancies, and higher CRP levels were associated with worse OS in patients with lymphoma." (PMID 37460979, 2023). "In different solid tumors, as well as lymphomas, inflammatory markers, including leukocytes, neutrophils, lymphocytes, CRP, and neutrophil/lymphocyte ratio have been associated with higher mortality rates." (PMID 26321026, 2015). "C-reactive protein, thymidine kinase 1, and haptoglobin have been most extensively studied and commercialized in diagnostic tests, the TK Canine Cancer Panel and the Canine Lymphoma Blood Test." (PMID 27747218, 2016). "The results showed a trend toward increased AF incidence with elevated CRP levels across most cancer types, with the exception of lymphoma." (PMID 41387931, 2025). "In RA, high inflammatory burden—manifested by markedly elevated C-reactive protein (CRP) and rapid joint destruction—correlates with lymphoma risk." (PMID 41567225, 2025). "Leukocyte and CRP levels were notably elevated in patients diagnosed with hematological malignancies, particularly leukemias and lymphomas." (PMID 41024922, 2025). "Other factors increasing the risk of developing ICANS include elevated serum levels of C-reactive protein (CRP) and ferritin, lymphoma type, disease burden, and the specific CAR T-cell product." (PMID 40278905, 2025). "Our results were in line with previous research also demonstrating a prognostic value for CRP concentrations in lymphoma." (PMID 37460979, 2023). "This study aimed to examine the significance of the serum CRP biomarker in predicting the prognosis of dogs with lymphoma." (PMID 36718344, 2022). "Median value of pre-treatment levels of serum CRP and circulating inflammatory parameters in lymphoma dogs." (PMID 36718344, 2022). "The clinical staging distributions in dogs with lymphoma that was affected by high and low levels of serum CRP are shown in Table-2." (PMID 36718344, 2022). "In particular, the univariate regression analysis indicated that the NLR, PLR, TP, albumin, LDH, and CRP were prognostic factors for VTE development in the patients with lymphoma." (PMID 35439998, 2022). "This study suggests that serum CRP concentrations have the potential in clinical applications for assisting clinical decision-making on the WHO stage in lymphoma dogs." (PMID 36718344, 2022). "In the multivariate regression model, the NLR and CRP were found to be independent prognostic factors for VTE development in the patients with lymphoma (p = 0.046, OR = 1.043, 95% CI: 1.001–1.087 and p = 0.024, OR = 1.007, 95% CI: 1.001–1.013, respectively)." (PMID 35439998, 2022). "Hemangiosarcoma, nasal adenocarcinoma, cholangiocellular carcinoma, acute lymphoblastic leukemia, malignant histiocytosis, lymphoma, malignant mesothelioma, and intestinal adenocarcinoma were found to significantly increase CRP concentration." (PMID 36290272, 2022). "In this study, the median value for the CRP concentration in all lymphoma cases is 56.65 mg/L (Table-3)." (PMID 36718344, 2022). "Serum CRP concentrations can assist clinical decision-making on the WHO stage in lymphoma dogs in clinical applications." (PMID 36718344, 2022). "In the univariate regression analysis, the NLR, PLR, TP, albumin, LDH, and CRP were found to be prognostic factors for VTE development in the patients with lymphoma." (PMID 35439998, 2022). "For all lymphoma dogs, the majority of 27 dogs (79.4%) had CRP concentrations >10 mg/L; however, seven dogs (20.6%) demonstrated low CRP concentrations ≤10 mg/L (Table-1)." (PMID 36718344, 2022).
lymphoma (continued). "In this study, the use of serum CRP was compared with pre-treatment albumin and circulating inflammatory markers in lymphoma dogs at various stages." (PMID 36718344, 2022). "Distribution of clinical staging affected by high (more than 10 mg/L) and low (≤10 mg/L) level of serum CRP in dogs with lymphoma." (PMID 36718344, 2022). "Multiple studies have revealed that the ratio of various types of circulating blood cells can be used to predict lymphoma prognosis based on the relationship between inflammation and lymphoma, as demonstrated by serum CRP elevation and circulating blood cells." (PMID 36718344, 2022). "Our analysis found that the inflammatory markers correlated well with the risk for VTE development in patients with lymphoma, with NLR and CRP being the most accurate VTE predictive markers." (PMID 35439998, 2022). "In this study, dogs with advanced-stage (Stages IV and V) lymphoma had significantly higher CRP levels than dogs with Stages I−III lymphoma (p = 0.00048)." (PMID 36718344, 2022). "The ROC curve analysis indicated acceptable specificity and sensitivity values of the NLR, PLR, and CRP in predicting VTE in the patients with lymphoma." (PMID 35439998, 2022). "The optimal CRP cutoff value of 54.1 mg/L had 85.71% sensitivity and 85% specificity for predicting lymphoma dogs in the advanced stages of the disease." (PMID 36718344, 2022). "C-reactive protein levels were significantly higher in lymphoma dogs in advanced stages (IV and V) than in lymphoma dogs in Stages I–III." (PMID 36718344, 2022). "According to the ROC curve analysis, a CRP cutoff level of 54.1 mg/L indicates advanced-stage canine lymphoma, which can be used as a biomarker to predict cancer dissemination." (PMID 36718344, 2022). "This study aimed to examine pre-treatment serum CRP levels in relation to serum albumin and other circulating inflammatory parameters in dogs with advanced-stage lymphoma." (PMID 36718344, 2022). "In dogs with multicentric lymphoma, low, physiological CRP level was shown to be related to obtaining remission." (PMID 36290272, 2022). "Overall, lymphoma patients had rising inflammatory markers in routine laboratory testing at the time of clinical deterioration, including C-reactive protein (CRP) and IL-6 serum levels." (PMID 34235400, 2021). "CRP is an acute phase protein that has been previously reported as a useful tool for evaluating remission status in canines with lymphoma and HSA." (PMID 34187493, 2021). "A Chinese study on a group of lymphoma patients showed that post-treatment SUVmax values were significantly correlated with post-treatment CRP values." (PMID 32098356, 2020). "Biochemical tests must include lactate dehydrogenase (LDH) and β2-microglobulin, which are also reliable diagnostic and response criteria markers, C-reactive protein (CRP), uric acid, and other tests related to organ damage from the lymphoma." (PMID 30286805, 2018). "Measurement of fucosylated serum proteins as well as SAA, CRP, and haptoglobin has been evaluated as biomarkers of lymphoma disease and treatment monitoring." (PMID 27747218, 2016). "Using a surface-enhanced laser desorption ionization time of flight (SELDI-TOF) protein detection method, another group identified CRP and haptoglobin as potential biomarkers of lymphoma and created ELISA-based assays for those proteins." (PMID 27747218, 2016). "As a sole biomarker, serum CRP has been shown to be elevated at diagnosis in most dogs with lymphoma compared to healthy dogs, and to decrease to a range indistinguishable from healthy dogs when in remission." (PMID 27747218, 2016). "Median CRP concentration was increased in all groups with neoplastic lymphatic disorders like lymphomas, malignant lymphoma, and multiple myeloma." (PMID 21430962, 2011). "Further, B-symptoms related to malignancy may commonly be mistaken for routine infections, and some newly diagnosed lymphoma and MM patients demonstrate elevated C-reactive protein levels." (PMID 39174738, 2024).
lymphoma (continued). "Interestingly, CRP levels are significantly higher in lymphoma dogs in the advanced stage (Stages IV and V, p = 0.00048), as indicated by the box and whisker plot (Figure-1)." (PMID 36718344, 2022). "The AUC indicated that serum CRP level has a good ability to differentiate between Stages I–III and advanced stages of lymphoma in dogs in ROC analysis, and 54.1 mg/L was the cutoff CRP level with the appropriate balance for sensitivity (85.71%) and specificity (85.00%)." (PMID 36718344, 2022). "C-reactive protein could be used as a prognostic biomarker for canine lymphoma, indicating advanced-stage and disseminated disease." (PMID 36718344, 2022). "Furthermore, the ROC curve was used to investigate the usefulness of serum CRP levels in determining disseminated disease in lymphoma dogs." (PMID 36718344, 2022). "The canine lymphoma blood test values, derived from C-reactive protein and Hp, could predict the remission status and relate to the survival time." (PMID 35765478, 2022). "We analyzed a variety of clinical factors (gender, age, risk stratification, clinical stage, CAR-T cell dose, serum peak concentration of IL-6 and CRP, CD4/CD8, etc.)that may be associated with CRS in patients with lymphoma, separately." (PMID 33708205, 2021). "We found that the Kyn/Trp ratio in all lymphoma survivors analyzed was significantly correlated with other markers of immune activation and inflammation, such as measurable levels of IL-6, neopterin and CRP." (PMID 31923274, 2020). "However, no previously reported data indicate that NLR, PLR, Fibrinogen, or CRP can be used in a clinically meaningful way to help differentiate among anterior mediastinal tumors (TETs, lymphomas, and germ cell tumors) or to facilitate TET diagnosis." (PMID 29774108, 2018). "C-reactive protein has been evaluated by several groups as a biomarker of lymphoma activity." (PMID 27747218, 2016). "Nine variables in the training cohort were considered to be independent risk factors for patients with lymphoma in the final model: age, Ann Arbor Stage, pathologic type, B symptoms, chemotherapy, targeted therapy, lactate dehydrogenase (LDH), β2-microglobulin and C-reactive protein (CRP)." (PMID 37460979, 2023). "The NLR, PLR, ESR, CRP, and LDH were significantly higher in the patients with lymphoma with VTE, whereas the TP and albumin were significantly lower in those patients." (PMID 35439998, 2022). "Several biomarkers such as the C-reactive protein (CRP) and albumin are able to reflect the inflammatory response in lymphoma patients." (PMID 34415426, 2022). "Likely due to the small number of non-responders, univariate analyses did not reveal statistically significant predictors of response, including disease status, lymphoma subtype, previous autologous transplant, or baseline LDH, ferritin, and CRP levels." (PMID 34893603, 2021). "Higher CRP levels were detected in the dogs with diagnoses of MMGT (18.45 mg/L), lymphoma (13.24 mg/L), HCC (26.85 mg/L), TCC (3.68 mg/L), HSA (15.91 mg/L), PAC (8.69 mg/L), and Mel (28 mg/L)." (PMID 30411459, 2019). "The erythrocyte sedimentation rate (ESR), C-reactive protein (CRP), neutrophil-to-lymphocyte ratio (NLR), platelet-to-lymphocyte ratio (PLR), lactate dehydrogenase (LDH), total protein (TP), and albumin were assessed in 706 patients with newly diagnosed or relapsed lymphoma." (PMID 35439998, 2022). "Several reports have proposed that the CRP level might predict survival in patients with lymphoma, although the role of CRP as a biomarker for lymphoma has not been established." (PMID 31004109, 2019). "Since we excluded patients with infections, the CRP level could be used as a possible biomarker for lymphoma, rather than as an inflammatory marker." (PMID 31004109, 2019). "The prognostic significance of CRP for lymphoma has not been fully examined." (PMID 23724031, 2013).
lymphoma (continued). "CRP is a nonspecific inflammation marker synthesized in response to acute inflammation or destruction of tissue cells, and over-expressed levels are demonstrated to be prognostic markers in various tumors, including lung, lymphoma, and, more recently, H and N cancers." (PMID 38668001, 2024). "CRP and ESR, as indicators of non-specific inflammatory activity, are both elevated during lymphoma disease activity but lack specificity for diagnosis." (PMID 40766055, 2025). "In our study, the NLR, PLR, ESR, CRP, and LDH were significantly higher in the patients with lymphoma with VTE than in those without VTE, whereas the TP and albumin were significantly lower in the patients with lymphoma with VTE than in those without VTE." (PMID 35439998, 2022). "Compared with patients without VTE, the NLR, PLR, ESR, CRP, and LDH were significantly higher in the patients with lymphoma with VTE (p = 0.001, p = 0.001, p = 0.023, p < 0.001, and p = 0.035, respectively), whereas the TP and albumin were significantly lower (p = 0.024 and p = 0.032, respectively)." (PMID 35439998, 2022).
pulmonary hypertension (61 papers, 2010 to 2026). Increased pressure within the pulmonary circulation due to lung or heart disorder. "The MLR and CRP/albumin ratio were associated with development of pulmonary arterial hypertension (p = 0.036, p = 0.006), and the lymphocyte/HDL ratio was associated with newly developed interstitial lung disease (p = 0.004)." (PMID 41464713, 2025). "Another network meta-analysis study suggested that statins reduced the risk of all-cause and cause-specific mortality, pulmonary hypertension, and the level of C-reactive protein (CRP), IL6, IL8, and TNF-α in COPD patients." (PMID 36837454, 2023). "CRP can play a role in the pathogenesis of pulmonary-hypertension-associated COPD, and it was suggested as a systemic marker of the inflammatory process that occurs in COPD cases." (PMID 37873776, 2023). "A thorough binary analysis revealed a significant correlation between an SARC-F score of ≥4 and variables such as age, pulmonary arterial hypertension, albumin levels, and C-reactive protein in patients with SSc." (PMID 40095540, 2025). "In a study of patients with pulmonary arterial hypertension and chronic thromboembolic-derived PH, circulating c-reactive protein (CRP), a marker for generalized inflammation, is significantly higher in PH patients compared to controls." (PMID 38610760, 2024). "Lower LVEF, pulmonary hypertension, higher D-dimer, C-reactive protein, and B-type natriuretic peptide levels were predictors of poor outcomes." (PMID 37304946, 2023). "Capillary blood gas analysis enables the diagnosis of the obesity hypoventilation syndrome (OHS), which, in turn, can contribute to pulmonary hypertension, independently increasing serum levels of CRP." (PMID 36363559, 2022). "The CRP concentration can be used as a marker of endothelial arteritis and pulmonary hypertension in dogs infected with D. immitis." (PMID 34083932, 2021). "And using statins reduced C-reactive protein (CRP) and pulmonary hypertension (PH) in COPD patients, the SMD (95% CI) were − 0.62 (− 0.52,-0.72) and − 0.71 (− 0.85,-0.57), respectively." (PMID 30674312, 2019). "Another study went a step further and found a correlation between CRP concentrations with severity of pulmonary arterial damage and pulmonary hypertension in dogs with D. immitis." (PMID 29143665, 2017). "Among them, C-reactive protein (CRP) increases according to the severity of the disease; and a strong correlation between pulmonary hypertension and CRP has been observed." (PMID 29143665, 2017). "In this study, CRP was significantly increased in infected animals with mild or severe pulmonary hypertension." (PMID 29143665, 2017). "Increased CRP levels have been observed in patients with pulmonary hypertension and are positively correlated with right atrial pressure (RAP), WHO-FC, 6MWD, and survival outcomes, suggesting a strong link between inflammation and cardiopulmonary decompensation." (PMID 41225615, 2025). "Particularly, the proportions of SSc patients suffering from SSc-related vascular complications such as digital ulcerations, Raynaud’s syndrome, or pulmonary arterial hypertension were comparable among both CRP− groups, as were the proportions of vasodilatory drug users (p > 0.05)." (PMID 39564499, 2024). "C-reactive protein is a potential marker for pulmonary hypertension in canine dirofilariasis or for chronic lymphatic pathology in human wuchereriasis and so interactions affecting the ability of this pentraxin to elicit or modulate a response are biologically relevant." (PMID 30622255, 2019). "This relationship between CRP and pulmonary hypertension was supported by the results of another study, which also evaluated haptoglobin, albumin and PON-1, and confirmed the relationship between pulmonary hypertension and acute phase response, especially in the positive APP CRP and haptoglobin." (PMID 29143665, 2017).